ATP13A4-AS1 (ATP13A4 antisense RNA 1)
Gene: Long non-coding RNA gene on chromosome 3 (193,506,780 to 193,555,586, forward strand). Ensembl gene ENSG00000225473.
Diseases named in the same sentence as ATP13A4-AS1 in open-access papers:
ATP13A4-AS1 is named in the same sentence as 1 disease in open-access papers, as found by Europe PMC text mining. Sharing a sentence is not in itself a finding about the gene and the disease. The quoted sentences say what the papers report.
cancer (1 paper, 2021). A tumor composed of atypical neoplastic, often pleomorphic cells that invade other tissues. "ATP13A4 antisense RNA 1 (ATP13A4-AS1) is an antisense long noncoding RNA (lncRNA) derived from ATP13A4 with an unknown function in cancer." (PMID 34026765, 2021).